IGF2BP3 (insulin like growth factor 2 mRNA binding protein 3)
Diseases named in the same sentence as IGF2BP3 in open-access papers (continued):
Sharing a sentence is not in itself a finding about the gene and the disease.
liver cancer (22 papers, 2013 to 2026). An epithelial or non-epithelial malignant neoplasm that arises from the liver. "IGF2BP3 was associated with immune cell infiltration in patients with liver cancer and affected prognosis." (PMID 34026613, 2021). "The combination of IGF2BP3 inhibition with anti‐CD47 therapy markedly suppresses liver cancer growth." (PMID 39802639, 2025). "Although IGF2BP3’s involvement in ferroptosis regulation has been documented in both lung and liver cancers, recent studies emphasize its cancer type-specific regulatory mechanisms mediated by divergent downstream targets." (PMID 40530014, 2025). "For example, ALKBH5 has been reported to be involved in liver cancer development and immune microenvironment shaping, and IGF2BP3 promotes AML progression and stemness maintenance." (PMID 38822351, 2024). "Insulin-like growth factor 2 mRNA-binding protein 3 (IGF2BP3) was identified as an independent prognostic factor for liver cancer." (PMID 38992083, 2024). "In conclusion, IGF2BP3 acts as a tumor-promoting factor in liver cancer and is involved in resistance to therapeutic drugs." (PMID 37298373, 2023). "It has been shown that LINC00467 promotes cell proliferation and migration in liver cancer by binding to IGF2BP3 to enhance the stability of its cis-target genes." (PMID 34362879, 2021). "Particularly, we found that IGF2BP3 exhibited significantly higher expression in three kidney cancers and liver cancer." (PMID 33575259, 2020). "We analyzed the expression of SMG5, EZH2, FBLL1, ZNF239, and IGF2BP3 in liver cancer using the Oncomine database." (PMID 33297932, 2020). "Although displaying less convincing IGF2BP3 staining in liver cancer, IGF2BP3 expression was correlated with cell proliferation by co-expression of ki67." (PMID 23069990, 2013). "Notably, high expression of IGF2BP3 significantly reduced survival time only in liver cancer, with this difference being statistically significant." (PMID 40765570, 2025). "Moreover, IGF2BP3 has been shown to modulate ferroptosis in lung cancer and liver cancer." (PMID 40530014, 2025). "IGF2BP3, the protein encoded by this gene was primarily found in the nucleolus, and also known as that HBV-pgRNA (pregenomic RNA) could be a potential biomarker to predict clinical outcome and recurrence of HCC, thus the pgRNA-IGF2BP3 axis had a crucial function in HBV-associated liver cancer." (PMID 37466793, 2023). "Key resistance pathways include: lactylated IGF2BP3 activating PCK2-NRF2 to counter lenvatinib-induced stress; ALDOA lactylation enhancing liver cancer stem cell self-renewal for chemoresistance; MOESIN lactylation in Regulatory T cells (Tregs) weakening anti-PD-1 efficacy." (PMID 41685085, 2026). "Moreover, elevated IGF2BP3 levels correlate with poorer overall survival (OS) and progression-free survival (PFS) in liver cancer patients." (PMID 40765570, 2025). "Taken together, these results indicate that SLC27A5 can suppress liver cancer progression by interacting with IGF2BP3, independent of its enzyme activity." (PMID 38059827, 2024). "IGF2BP3, an m6A reader, facilitates macrophage infiltration and M2 polarization by upregulating the expression of CCL5 and transforming growth factor beta 1 (TGF‐β1), which, in turn, inhibits CD8+ T cell activation and contributes to the progression of liver cancer." (PMID 39802639, 2025).
ovarian carcinoma (22 papers, 2013 to 2026). A malignant neoplasm originating from the surface ovarian epithelium. "Previous study has revealed that IGF2BPs contribute to mRNA stability and IGF2BP1 and IGF2BP3 are associated with poor disease outcome in ovarian cancer." (PMID 35869392, 2022). "According to the categorized IGF2BP3 expression data, the Kaplan-Meier survival curves demonstrate significant associations of IGF2BP3 overexpression with ovarian cancer specific survival in the AOVT and overall survival in the COEUR cohort." (PMID 32083017, 2019). "In ovarian cancer, high expression of IGF2BP3 was associated with poor survival, and women diagnosed at advanced stages with elevated IGF2BP3 was at higher risk of developing chemoresistance." (PMID 30822312, 2019). "However, there was contradictive result suggesting that IGF2BP3 expression was positively associated with improved survival in ovarian cancer." (PMID 36891946, 2023). "Interestingly, IGF2BP3 has been found to be associated with chemotherapy resistance and poor prognosis of ovarian cancer." (PMID 33763357, 2021). "However, in ovarian cancer IGF2BP3 expression has been associated with increased survival." (PMID 38092752, 2023). "For example, IGF2BP2 gene is a relatively common event in comparison to the amplification of the other IGF2BPs family members, IGF2BP1 and IGF2BP3, occurring in ~15–27% of ovarian cancers." (PMID 35717493, 2022). "In ovarian cancer, combined high expression of IGF2BP3 and of Lin28B, another RNA-binding protein, was strongly associated with chemoresistance and poor disease outcome, based on elevated expression of hCTR1, a copper transporter involved in platinum uptake." (PMID 35615150, 2022). "According to literature reports, IGF2BP3 can promote the carcinogenesis of ovarian cancer and pancreatic duct adenocarcinoma." (PMID 35047058, 2022). "Among the various cancers for which an upregulation or de novo synthesis for IGF2BP3 was reported, lung, gastrointestinal, and ovarian cancers are the most frequently reported." (PMID 23069990, 2013). "Additionally, research into IGF2BP3’s role in ovarian cancer (OC) identifies the small molecule AE-848, which disrupts IGF2BP3’s interaction with target mRNAs, leading to decreased levels of factors like c-MYC, VEGF, and CDK2." (PMID 39456596, 2024). "In addition, IGF2BP3 affects the occurrence and development of ovarian cancer through other pathways that need additional study." (PMID 37298373, 2023). "Differences in ovarian carcinoma subtypes of these studies may be accountable for these contradictory observations, indicating that IGF2BP3 played diverse biological effects in various disease." (PMID 36891946, 2023). "IGF2BP3 (also known as IMP3), also expressed in ovarian cancer cells, is a part of the IGF2BP family, which is associated with the development, progression and prognosis of ovarian cancer." (PMID 34794452, 2021). "Notably, there is contradictive evidence for ovarian cancer suggesting IGF2BP3 expression to correlate with an improved survival." (PMID 23069990, 2013). "Consistent with our results, IGF2BP2 and IGF2BP3 were significantly increased in ovarian cancer, whereas FTO was significantly decreased in ovarian cancer." (PMID 38714753, 2024). "IGF2BP3 increases the stability of SIX4 mRNA, thus promoting ovarian cancer cell proliferation, migration, and invasion, as well as tube formation." (PMID 37298373, 2023). "For example, the expression of HNRNPA2B1 was positively correlated with the expressions of IGF2BP3, YTHDC1, YTHDF2, RBM15, and ZC3H13 in ovarian cancer." (PMID 33225598, 2021). "Two GEO databases demonstrated that 7 readers (HNRNPC, IGF2BP1, IGF2BP2, IGF2BP3, RBMX, YTHDC2, and YTHDF2) and 3 writers (METTL3, RBM15, and RBM15B) were more highly expressed in ovarian cancer than in ovarian surface epithelium or normal peritoneum tissues (GEO14407 and GEO12470)." (PMID 33225598, 2021).
ovarian carcinoma (continued). "Given the theory implicating the distal oviduct as a common source for epithelial ovarian cancer, we analyzed the GSE69428 data and showed that the expression of IGF2BP2, IGF2BP3, RBMX, YTDHF1, and RBM15 was also higher in ovarian cancer than in normal oviduct." (PMID 33225598, 2021).
cervical carcinoma (21 papers, 2020 to 2025). A carcinoma arising from either the exocervical squamous epithelium or the endocervical glandular epithelium. "Survival analysis demonstrated that IGF2BP3 had a potential association with the survival of cervical cancer patients." (PMID 37877353, 2023). "IGF2BP3 is associated with chemotherapy resistance in cervical cancer by regulating PDK4 mRNA stability." (PMID 37298373, 2023). "Consistently, the CCK‐8 assay results showed that IGF2BP3 mutation significantly inhibited cervical cancer cell growth." (PMID 37877353, 2023). "Our findings elucidate an important mechanism underlying the regulation of IGF2BP3 in cervical cancer and provide a new modulation strategy for cervical cancer treatment." (PMID 37877353, 2023). "A ubiquitination assay demonstrated that mutation of IGF2BP3 at K213 could block Parkin‐mediated ubiquitination, reduce the oncogenic function of IGF2BP3 and inhibit cervical cancer cell proliferation." (PMID 37877353, 2023). "Thus, in future studies, we will analyse the ubiquitination level of IGF2BP3 in human cervical cancer tissues and its association with the prognosis of cancer patients." (PMID 37877353, 2023). "Consequently, the tumourigenesis of cervical cancer is also inhibited by IGF2BP3 mutation." (PMID 37877353, 2023). "In particular, in gastric, esophageal squamous cell, and cervical cancers, IGF2BP3 levels are significantly elevated, showing a strong correlation with lymph node metastasis and poorer prognosis." (PMID 40801655, 2025). "This study links the oncofetal RNA-binding protein IMP3 (IGF2BP3) to coordinated control of mitochondrial function and lipid metabolism in cervical cancer models, integrating cell-intrinsic physiology with transcriptomic and lipidomic readouts." (PMID 41614778, 2025). "It has been shown that in cervical cancer, IGF2BP3 promotes lipid metabolism reprogramming by upregulating the expression of stearoyl coenzyme A desaturase (SCD), which subsequently promotes the survival and proliferation of tumor cells." (PMID 40801655, 2025). "The differential gene was obtained by identifying RNA‐Seq in clinical tissues of cervical cancer, and IGF2BP3 was identified as the common target gene for ATL III to act on HeLa and SiHa cells." (PMID 38358034, 2024). "In this study, we found that ATL III promotes apoptosis and regulates epithelial–mesenchymal transition (EMT) in cervical cancer cells (HeLa and SiHa cells) and that IGF2BP3 is a common target gene of ATL III in HeLa and SiHa cells." (PMID 38358034, 2024). "And it has been reported that IGF2BP3 can promote cervical cancer cell proliferation by binding to the mRNA of RAB2B." (PMID 38355626, 2024). "In summary, our research showed that IGF2BP3 is involved in the migration and invasion of cervical cancer cells in vitro." (PMID 38358034, 2024). "This study shows that ATL III can regulate EMT in cervical cancer cells and that overexpression of IGF2BP3 can reverse the inhibition of HeLa and SiHa cell proliferation." (PMID 38358034, 2024). "In general, our research showed that ATL III inhibits the migration and invasion of cervical cancer cells by regulating IGF2BP3 through ETV5." (PMID 38358034, 2024). "The wound‐healing assay showed that overexpression of IGF2BP3 significantly promoted the migration ability of cervical cancer cells, whereas silencing IGF2BP3 inhibited the migration ability of cervical cancer cells compared with that in the control group." (PMID 38358034, 2024). "To explore the mechanism of IGF2BP3 in cervical cancer cells, we overexpressed or silenced IGF2BP3 in cervical cancer cells, and WB experiments were used to verify the expression of EMT biomarker proteins after transfection." (PMID 38358034, 2024). "The expression level of IGF2BP3 in cervical cancer cells was proportional to their migration and invasion abilities." (PMID 38358034, 2024).
cervical carcinoma (continued). "In our study, IGF2BP3 promoted the migration and invasion of HeLa and SiHa cells in vitro, indicating that IGF2BP3 plays a vital role in the invasion and metastasis of cervical cancer." (PMID 38358034, 2024). "After ATL III treatment, the migration and invasion abilities of cervical cancer cells were obviously reduced, but these effects were attenuated after overexpression of IGF2BP3." (PMID 38358034, 2024). "On the whole, our study elucidated that IGF2BP3 functions in CC oncogenesis and progression and provides a new clinical treatment tactics to cervical cancer patients." (PMID 38355626, 2024). "IGF2BP3 expression is negatively correlated with Parkin expression in human cervical cancer cells and tissues." (PMID 37877353, 2023). "LncRNA KCNMB2-AS1 served as a competing endogenous RNA to abundantly sponge miR-130b-5p and miR-4294, resulting in the upregulation of IGF2BP3 in cervical cancer." (PMID 37365581, 2023). "RAB2B is overexpressed in cervical cancer and interacts with IGF2BP3 to promote cell growth and proliferation." (PMID 36712921, 2023). "Gene Expression Omnibus (GEO) analysis demonstrated that IGF2BP3 was significantly up‐regulated in cell lines and tissues of human cervical cancer from GDS3233." (PMID 37877353, 2023). "In the present study, we explored the regulation of the m6A reader IGF2BP3 in human cervical cancer in detail by Parkin and revealed an important role of IGF2BP3 ubiquitination in maintaining its oncogenic function." (PMID 37877353, 2023). "In this study, we investigated the regulation of IGF2BP3 by the E3 ubiquitin ligase Parkin and identified its ubiquitination site in human cervical cancer." (PMID 37877353, 2023). "Taken together, IGF2BP3, as a key molecule in multiple mechanisms, plays a tumor-promoting role in cervical cancer." (PMID 37298373, 2023). "IGF2BP3 is ubiquitinated and regulated by the E3 ubiquitin ligase Parkin in human cervical cancer and ubiquitination modification plays an important role in modulating IGF2BP3 function." (PMID 37877353, 2023). "LncRNA KCNMB2-AS1 that improves IGF2BP3 expression via sponging miR-130b-5p and miR-4294 is stabilized by IGF2BP3 in an m6A-mediated manner, synergistically accelerating cervical cancer cell growth." (PMID 37280679, 2023). "As one isoform of IGF2BP, IGF2BP3 has been considered a biomarker in different types of cancer, including cervical cancer." (PMID 37877353, 2023). "ACIN1 is stabilized through METTL3/IGF2BP3, boosting proliferation and migration of cervical cancer cells." (PMID 37280679, 2023). "cBioPortal analysis displayed an inverse correlation of IGF2BP3 with Parkin in human cervical cancer." (PMID 37877353, 2023). "The RBP IGF2BP3 was ubiquitinated by the E3 ubiquitin ligase Parkin in human cervical cancer, which occurred at K213 in the first KH domain of IGF2BP3." (PMID 37877353, 2023). "Conversely, Parkin was down‐regulated in most cervical cancer cell lines, which was opposite to the expression levels of IGF2BP3." (PMID 37877353, 2023). "Researchers found that circCDKN2B-AS1 cooperated with IGF2BP3 to regulate the stability of HK2 mRNA in cervical cancer, thereby promoting aerobic glycolysis and cancer progression." (PMID 37298373, 2023). "Here, mass spectrometry analysis showed that the E3 ubiquitin ligase Parkin promoted IGF2BP3 polyubiquitination in cervical cancer." (PMID 37877353, 2023). "Nude mice were subcutaneously injected with sufficient cervical cancer cells, including HeLa‐Parkin cells with wild‐type or mutant IGF2BP3 expression." (PMID 37877353, 2023). "Another study discovered that the YTHDF1/eEF-2 complex and IGF2BP3 increase the translation elongation and mRNA stability of pyruvate dehydrogenase kinase 4 to control glycolysis in cervical cancer cells." (PMID 36091006, 2022).
cervical carcinoma (continued). "Mechanically, KCNMB2-AS1 was predominantly located in the cytoplasm and served as a ceRNA to abundantly sponge miR-130b-5p and miR-4294, resulting in the upregulation of IGF2BP3, a well-documented oncogene in cervical cancer." (PMID 35406713, 2022). "According to a recent study, KCNMB2-AS1 and IGF2BP3 established a positive regulatory circuit that increased KCNMB2-AS1’s tumorigenic activity in cervical cancer." (PMID 36091006, 2022). "KCNMB2-AS1 and IGF2BP3 formed a positive regulatory circuit that increased the tumorigenic effect of KCNMB2-AS1 in cervical cancer." (PMID 36058934, 2022). "In addition, the rescue experiment showed that ATL III regulates the EMT of cervical cancer cells by downregulating IGF2BP3." (PMID 38358034, 2024). "Currently, the mechanism of IGF2BP3 in cervical cancer is obscure." (PMID 38358034, 2024). "During this research, the immunohistochemical (IHC) staining announced that compared with adjacent normal tissues, IGF2BP3 expression was obviously higher in CC tissues and it is a positive correlation between high IGF2BP3 expression and cervical cancer staging." (PMID 38355626, 2024). "Finally, we explored the possible role of ETV5 as a transcription factor in the role of ATL III in cervical cancer via IGF2BP3." (PMID 38358034, 2024). "High expression of IGF2BP3 in cervical cancer has a positive correlation with poor prognosis." (PMID 38355626, 2024). "Here, we investigated the effects of ATL III on cervical cancer cells at different concentrations and found that ATL III downregulates insulin‐like growth factor 2 mRNA‐binding protein 3 (IGF2BP3), which was found to be highly expressed in cervical cancer tissue by RNA‐Seq." (PMID 38358034, 2024). "In addition, transwell experiments showed that cervical cancer cells overexpressing IGF2BP3 showed stronger invasion ability than control cells." (PMID 38358034, 2024). "Finally, the effect of IGF2BP3 ubiquitination on cervical cancer growth was determined using tumour spheroids formation." (PMID 37877353, 2023). "Researchers have identified IGF2BP3 as a tumor-promoting factor in cervical cancer." (PMID 37298373, 2023). "IGF2BP3 mutation resulted in the loss of its function in the activation of oncogenic PI3K and MAPK signalling pathways, including mitophagy, which resulted in the inhibition of cervical cancer cell growth and tumourigenesis." (PMID 37877353, 2023). "Moreover, LncRNA KCNMB2-AS1 and IGF2BP3 formed a positive regulatory circuit that enlarged the tumorigenic effect of KCNMB2-AS1 in cervical cancer." (PMID 37365581, 2023). "Studies on IGF2BP3 have provided new insights into cervical cancer treatment." (PMID 37298373, 2023). "In addition, GEPIA analysis showed that IGF2BP1/2/3 were up‐regulated in cervical cancer tissues, but only the differential expression of IGF2BP3 was significant." (PMID 37877353, 2023). "In addition, researchers also found that IGF2BP3 is involved in doxorubicin resistance in cervical cancer." (PMID 37298373, 2023). "To validate this hypothesis, we determined IGF2BP3 expression levels in a series of cervical cancer cell lines." (PMID 37877353, 2023). "High expression of lncRNA KCNMB2-AS1 is positively correlated with poor prognosis of cervical cancer by upregulating the oncogene IGF2BP3, which in turn increases the stability of KCNMB2-AS1; lncRNA ZFAS1 promotes the metastasis of cervical cancer by suppressing miR-647 mediated by METLL3." (PMID 35432630, 2022). "Thus, KCNMB2-AS1 and IGF2BP3 formed a positive regulatory circuit that enlarged the tumorigenic effect of KCNMB2-AS1 in cervical cancer." (PMID 35406713, 2022). "Thus, understanding the role of IGF2BP3 in tumourigenesis could provide new insights into cervical cancer therapy." (PMID 37877353, 2023). "However, more evidence is needed, and IGF2BP3 may be developed as a prognostic biomarker, accelerating the discovery of treatment targets for cervical cancer." (PMID 37877353, 2023).